PSMD2 (proteasome 26S subunit ubiquitin receptor, non-ATPase 2)
Diseases named in the same sentence as PSMD2 in open-access papers (continued):
Sharing a sentence is not in itself a finding about the gene and the disease.
cancer (14 papers, 2016 to 2026). A tumor composed of atypical neoplastic, often pleomorphic cells that invade other tissues. "Additionally, more and more studies report that PSMD2 is tightly linked with immunosuppression in multiple cancer types." (PMID 36505799, 2022). "And based on the tissue microarray composed of 98 NSCLC and 82 adjacent cancer samples, we found stronger staining and higher IHC score of PSMD2 in NSCLC tissues than adjacent tissues." (PMID 37864031, 2023). "Through analyzing the transcriptional data of the GTEx and TCGA database, the expression values of PSMD2 were firstly investigated in multiple cancers involving over 10000 cancer and normal tissue samples." (PMID 36505799, 2022). "Cancer Single-cell State Atlas (CancerSEA) was used to explore the cancer functional status of PSMD2 at single-cell resolution." (PMID 35754829, 2022). "Given that the vital roles of PSMD2 in BCa, and the expression levels of PSMD2 were widely elevated in the vast majority of cancers, the roles of PSMD2 were subsequently explored in pan-cancer." (PMID 36505799, 2022). "Previous studies demonstrated that upregulation of PSMD2 is correlated with poor prognosis in many cancers." (PMID 35754829, 2022). "Compared with normal tissue controls, the expression of PSMD2 was upregulated in 13 cancer types and only downregulated in Kidney Chromophobe." (PMID 35754829, 2022). "To capture the expression of PSMD2 at single-cell resolution and its correlation with cancer functional states, we conducted an analysis on CancerSEA." (PMID 35754829, 2022). "In the NDRG1 module, PSMD2 is overexpressed in many cancer cells, whereas PABPC1, EIF4G1, EIF3H, EIF3E, and EIF3K are RNA translational control members." (PMID 26735889, 2016). "PSMD2 is a newly identified receptor in the 19S regulatory particle of the proteasome, and its aberrant expression has been correlated with the progression of some types of cancer." (PMID 36998052, 2023). "Applications of proteasome or mTOR inhibitors such as rapamycin derivatives to enhance cancer cell autophagy could therefore be a promising treatment strategy for ESCC with PSMD2 overexpression." (PMID 36998052, 2023). "The gene encoding 26S proteasome non-ATPase regulatory subunit 2 (PSMD2) of the ubiquitin–proteasome system is an oncogene in various types of cancer." (PMID 36998052, 2023). "Furthermore, both functional enrichment analysis and CancerSEA results indicate PSMD2 expression is correlated with cell cycle, further suggesting that PSMD2 can regulate cell cycle to promote cancer progression." (PMID 35754829, 2022). "Notably, HIST1H1D, PSMD2, ANXA2 and SPTAN1 overexpression was associated with elevated protein content in cancer tissues, whereas KRT5 has been rarely observed at the protein level in these tissues." (PMID 32252346, 2020). "Moreover, PSMD2 was also reported to function as a cancer driver in multiple human malignancies." (PMID 36505799, 2022). "In addition, PSMD2 had an impact on prognosis in 42% (14/33) of all cancer types for OS." (PMID 36123629, 2022). "Therefore, whether asporin could mediate another intracellular substrate proteasomal degradation via binding with PSMD2 in different types of cancer, still needs to be uncovered." (PMID 31608236, 2019). "Of the 102 driver genes present in at least four networks, we found that PSMA, PSMB, and PSMD were the cancer driver genes with a crucial role in the proteasome pathway (with also RPN1/2, PSMA3/5/6/7, PSMB2/3/4/8/9, PSMD2/3/4/7/11/12/14)." (PMID 29304754, 2018). "In line with those previous studies, our results also suggested that PSMD2 and UCHL1 may have therapeutic potential as targets against cancer." (PMID 34398824, 2021). "As observed in the case of tongue, genes associated with overall cohort, IL1RAP, ANO1, RYK, AP2M1, MFN1 and PSMD2 were significant prognosticators only in the late stage not in early cancers." (PMID 31310629, 2019).
cancer (continued). "In conclusion, the comprehensive pan-cancer analysis presented here demonstrated that several PSM genes (e.g. PSMA1, PSMB4-5, PSMB8-10, PSMD2, PSMD4, PSMD11, PSME1-3, and PSMG3) may be putative biomarkers for determining prognosis and choice of treatment for different cancer types." (PMID 36123629, 2022).
infection (2 papers, 2022 to 2025). The state of being infected such as from the introduction of a foreign agent such as serum, vaccine, antigenic substance or organism. "On the contrary, MOPV infection led to the late (48 h) release of PSMD2, RPS11, HNRNPA3, ATP1A1, TARS1, and PRKAR1A, whereas significantly elevated levels of IGFBP3 were found at both timepoints." (PMID 35337059, 2022). "Co-IP assays confirmed the interaction between GANC and endogenous and exogenous PSMD1/PSMD2 in the non-infected group and upon H7N9 infection." (PMID 40263249, 2025).
PSMD2 also shares sentences with these, for which no sentence is quoted: cervical cancer (2 papers); acute lymphoblastic leukemia (1); adenocarcinoma (1); Alzheimer disease (1); amyotrophic lateral sclerosis (1); colon cancer (1); escherichia coli infection (1); gastric adenocarcinoma (1); gastric tumors (1); Hydrocephalus (1); Insulin resistance (1); lung diseases (1); melanoma (1); myelodysplastic syndrome (1); myeloid malignancies (1); neurological diseases (1); non-alcoholic fatty liver disease (1); prostate carcinoma (1); pyelonephritis (1); Salmonella Infections (1); serous ovarian cancer (1); thyroid (1).